NTRK3 (neurotrophic receptor tyrosine kinase 3)
Diseases named in the same sentence as NTRK3 in open-access papers (continued):
Sharing a sentence is not in itself a finding about the gene and the disease.
ovarian carcinoma (5 papers, 2017 to 2025). A malignant neoplasm originating from the surface ovarian epithelium. "NTRK3 had been reported to be a prognosis predictor of ovarian cancer based on the correlation between NTRK3 CNVs and platinum-sensitive and platinum-resistant recurrences." (PMID 33432021, 2021). "All these studies support our conclusion from this study that NTRK3 and LRP2 might be prognosis biomarkers for Chinese ovarian cancer patients." (PMID 33432021, 2021).
Spindle Cell Tumor (5 papers, 2022 to 2025). "In summary, we reported the first case of primary pancreas NTRK-rearranged spindle cell tumor with a special sclerosing epithelioid fibrosarcoma pattern harboring EVT6::NTRK3 gene fusions, CDKN2A/2B homozygous deletion, and ARID1A mutation." (PMID 40548109, 2025).
uterine sarcomas (5 papers, 2022 to 2025). "In this study, we reported that NTRK3 overexpression may also be associated with CNS metastasis in cervical or uterine sarcomas." (PMID 35572973, 2022). "In a recent study, the presence of lymphovascular invasion, necrosis, mitotic count ≥ 8/10 HPF and NTRK3 fusion were considered poor prognostic factors in NTRK-rearranged uterine sarcomas." (PMID 38151535, 2024). "In this report, we present the first case of STRN3::NTRK3 fused uterine sarcoma metastatic to the spleen, properly classified after the excision of the secondary distant localization." (PMID 39582973, 2024). "In NTRK-rearranged uterine sarcomas, NTRK1 is more frequently involved in gene fusions than NTRK3, and TPM3::NTRK1 fusion is the most common translocation reported." (PMID 38151535, 2024).
astrocytoma (4 papers, 2007 to 2024). "In our cohort of IDH-mutant diffuse glioma, EGFR Amp was found to co-occur with FGFR1, FGFR2, NTRK3 and RB1 alterations, which was not completely consistent in astrocytoma and oligodendroglioma." (PMID 38595969, 2024).
autism (4 papers, 2016 to 2021). Persistent deficits in social interaction and communication and interaction as well as a markedly restricted repertoire of activity and interest as well as repetitive patterns of behavior. "Alternatively, a growing body of evidence generated from genetic evaluation of ASD risk genes has identified NTRK3, the gene coding for TrkC, as a plausible candidate in autism." (PMID 27909399, 2016). "Furthermore, a genetic association was found between the NTRK3 gene and both autism and Asperger syndrome." (PMID 34207213, 2021).
cervical carcinoma (4 papers, 2021 to 2024). A carcinoma arising from either the exocervical squamous epithelium or the endocervical glandular epithelium. "Among these genes, low expression of MRVI1 and NTRK3 was associated with poor overall survival in cervical cancer." (PMID 35141152, 2021). "ROC curve analyses proved the diagnostic value of MRVI1 and NTRK3 in cervical cancer." (PMID 35141152, 2021). "Low expression levels of MRVI1 and NTRK3 were associated with poor prognosis of cervical cancer." (PMID 35141152, 2021). "Association between MRVI1 and NTRK3 methylation status and cervical cancer." (PMID 35141152, 2021). "Furthermore, low expression of MRVI1 and NTRK3 was associated with poor prognosis of cervical cancer." (PMID 35141152, 2021). "After integrated TSGs and survival-related genes, 2 overlapping genes (MRVI1 and NTRK3) were discovered and considered as the cervical cancer candidate TSGs." (PMID 35141152, 2021). "Compared with adjacent normal tissues, a significantly elevated methylation level of cg14384532 on NTRK3 was also found in cervical cancer tissues (p < 0.05)." (PMID 35141152, 2021). "The methylation levels and expression levels of MRVI1 and NTRK3 had the ability to effectively discriminate cervical cancer from healthy samples." (PMID 35141152, 2021). "The expression levels of MRVI1 (P = 0.002) and NTRK3 (P = 0.029) were significantly lower in cervical cancer than those in adjacent normal cervical tissues." (PMID 35141152, 2021). "Hypermethylated and down-regulated expression levels of TSGs MRVI1 and NTRK3 have been identified in the current study; however, the detail epigenetic regulatory mechanism under cervical cancer still needs further investigation." (PMID 35141152, 2021). "In order to verify the differential methylation levels of MRVI1 and NTRK3 between cervical cancer and adjacent normal cervical tissues, pyrosequencing experiments were conducted." (PMID 35141152, 2021). "In this study, hypermethylated and significantly lower expressions of TSGs MRVI1 and NTRK3 were discovered in cervical cancers than that in normal cervical tissues using the bioinformatics." (PMID 35141152, 2021). "Depending on the present study, NTRK3 expression was significantly lower in cervical cancer specimens than that in normal cervical tissues, and low NTRK3 expression was associated with a poor prognosis." (PMID 35141152, 2021). "MRVI1 and NTRK3 levels were all significantly lower in cervical cancers compared to normal cervical tissues in three cervical cancer related datasets (p < 0.05)." (PMID 35141152, 2021). "Although, the hypermethylation levels of MRVI1 and NTRK3 were verified in 9 cervical cancer tissues by pyrosequencing, the large number of clinical samples should be collected in further study." (PMID 35141152, 2021). "The differences of MRVI1 and NTRK3 expressions between cervical cancer specimens and normal cervical tissues were further verified via three GEO datasets." (PMID 35141152, 2021). "Similarly, hypermethylation status of NTRK3 was reported in cervical cancer through analyzing sequencing data and further validated in clinical samples." (PMID 38357305, 2024). "Additionally, elevated methylation levels of MRVI1 and NTRK3 promoter were further verified in cervical cancer tissues by pyrosequencing experiments." (PMID 35141152, 2021). "The study contributes to our understanding of the roles of MRVI1 and NTRK3 in cervical cancer." (PMID 35141152, 2021). "In summary, our results revealed that hypermethylation in the promoter regions of MRVI1 and NTRK3 genes might lead to low expression in cervical cancer." (PMID 35141152, 2021). "Moreover, GEO data showed that MRVI1 and NTRK3 were significantly decreased in cervical cancer tissues." (PMID 35141152, 2021). "Accuracy of MRVI1 and NTRK3 for predicting the prognosis of cervical cancer patients." (PMID 35141152, 2021). "Moreover, promoter hypermethylation levels of MRVI1 and NTRK3 were also found in our clinical cervical cancer samples." (PMID 35141152, 2021).
cervical carcinoma (continued). "In conclusion, the down-regulation of MRVI1 and NTRK3 may drive cervical cancer through hypermethylation of their promoters." (PMID 35141152, 2021). "Finally, the ROC results showed that the promoter methylation levels of MRVI1 and NTRK3 had the ability to discriminate cervical cancer from healthy samples." (PMID 35141152, 2021). "Therefore, MRVI1 and NTRK3 genes may play important roles in the occurrence and prognosis of cervical cancer." (PMID 35141152, 2021). "However, the research on NTRK3 gene in cervical cancer is rare." (PMID 35141152, 2021). "Specifically, the genes ABL1, BAX, FASN, and PLAU exhibited abnormally high expression levels in cervical cancer specimens, in stark contrast to BCL2, IGF1, and NTRK3, which were markedly under-expressed." (PMID 38988712, 2024).
eating disorder (4 papers, 2020 to 2022). A broad group of psychological disorders with abnormal eating behaviors leading to physiological effects from overeating or insufficient food intake. "Ntrk3 is associated with eating disorders, panic disorders and onset of childhood mood disorders." (PMID 36712851, 2022).
Ewing sarcoma (4 papers, 2022 to 2025). A small round cell tumor that lacks morphologic, immunohistochemical, and electron microscopic evidence of neuroectodermal differentiation. "The other two NTRK gene fusions in pediatrics were an LPP1::NTRK2 fusion (Ewing’s sarcoma), and a RAD51B::NTRK3 (PTC); we did not identify ETV6::NTRK3, TPR::NTRK1 – NTRK gene fusions were more commonly reported among pediatrics with solid tumors." (PMID 38967220, 2024).
mood disorder (4 papers, 2022 to 2024). A cognitive disorder a disturbance in which the person's mood is hypothesized to be the main underlying feature. "NTRK3 is thought to play a role in the changes in synaptic activity associated with childhood-onset mood disorders." (PMID 39062188, 2024). "NTRK3 is important for neurotrophin signaling, the regulation of synapse assembly, and synaptic plasticity; it also contributes to mood disorders." (PMID 39062188, 2024).
panic disorder (4 papers, 2021 to 2024). An anxiety disorder characterized by multiple unexpected panic attacks with persistent concern of recurring attacks. "First, human genetic studies found an association of polymorphisms in NTRK3, the gene that codes for TrkC, with panic disorder patients." (PMID 36882590, 2023). "Given genetic linkages of TrkC with panic disorder and some other neuropsychiatric conditions, we propose “synaptic phospho-pathology” as their underlying pathological mechanism, providing a novel animal model and new therapeutic insights into NTRK3-linked neuropsychiatric disorders." (PMID 39333774, 2024).
adenoma (3 papers, 2013 to 2020). A neoplasm arising from the epithelium. "NTRK3 mRNA expression was significantly lower in colorectal adenocarcinomas and adenomas as compared to the matched normal colon mucosa, which carried unmethylated NTRK3." (PMID 23874207, 2013). "Using this same PMR threshold, NTRK3 promoter methylation was found in 60% of adenomas (N = 55) and 10% of the normal colon samples (N = 98; normal versus cancer: p<0.0001; normal versus adenoma: p<0.0001)." (PMID 23874207, 2013). "Among the 20 adenoma and cancer samples, only 6 samples showed weak or moderate NTRK3 expression, while 9 out of 10 normal samples showed strong or moderate NTRK3 expression." (PMID 23874207, 2013). "Methylated NTRK3 was found in 67% of colorectal adenocarcinomas and 60% of adenomas." (PMID 23874207, 2013). "In addition, we performed bisulfite sequencing of the promoter region of NTRK3 in representative cases of normal colon epithelium, adenomas, and adenocarcinomas (5 samples/group) and correlated these results with those of the NTRK3 qMSP assay." (PMID 23874207, 2013). "NTRK3 promoter methylation in colorectal adenocarcinoma, adenoma and normal colon epithelium." (PMID 23874207, 2013). "The normal colon mucosa showed heterogeneous membrane and cytoplasmic staining using an anti-NTRK3 monoclonal antibody, whereas almost no expression was detected in most adenoma and cancer cases (N = 30)." (PMID 23874207, 2013).
anxiety disorder (3 papers, 2013 to 2016). A category of psychiatric disorders which are characterized by anxious feelings or fear often accompanied by physical symptoms associated with anxiety. "Another study identified an allele variant in functional miR-485-3p target sites of the neurotrophin-3 receptor gene (NTRK3) as a susceptibility factor for anxiety disorders." (PMID 23593016, 2013).
colon adenocarcinoma (3 papers, 2013 to 2018). "We next assessed NTRK3 mRNA expression in normal colon mucosa samples, colorectal adenomas, and primary colon adenocarcinomas." (PMID 23874207, 2013). "NTRK3 is methylated in 60% of colon adenomas and 67% of colon adenocarcinomas." (PMID 23874207, 2013).
epilepsy (3 papers, 2014 to 2020). A brain disorder characterized by episodes of abnormally increased neuronal discharge resulting in transient episodes of sensory or motor neurological dysfunction, or psychic dysfunction. "In a previous study, we have shown that DNA methylation regulated potential gene networks, pathophysiological pathways including PDGFR, EGFR, NTRK3(RTKs) as well as mTOR signaling and several other potential epilepsy-related genes associated with FCD type II." (PMID 33192309, 2020). "In this study we have identified DNA methylation-regulated potential gene networks, pathophysiological pathways including PDGFR, EGFR, NTRK3 (RTKs), and mTOR signalling in addition to several other potential epilepsy-related genes associated with FCD type II pathology." (PMID 30568293, 2018).
head and neck cancer (3 papers, 2018 to 2024). A primary or metastatic malignant neoplasm affecting the head and neck. "Of 38 ETV6::NTRK3 gene fusions detected, most were found in head and neck cancers (n = 22; 57.9%) followed by STS (n = 7; 18.4%)." (PMID 38925616, 2024). "The only NTRK fusion gene detected in head and neck cancer was ETV6::NTRK3 (n = 22)." (PMID 38925616, 2024). "The only fusion gene detected in head and neck cancer was ETV6::NTRK3 (n = 22); in STS, ETV6::NTRK3 (n = 7) and LMNA::NTRK1 (n = 5) were common." (PMID 38925616, 2024).
high-grade glioma (3 papers, 2020 to 2022). "Activating fusions of NTRK1, NTRK2, or NTRK3 occur in approximately 40% of pediatric high-grade gliomas and NTRK2 fusions in about 3% of pediatric pilocytic astrocytomas." (PMID 32906676, 2020). "The association of AF106564.1 with NTRK3 (ensembl ENSG00000140538) is also intriguing as NTRK genes code for tyrosine kinase receptors for growth factors in the CNS and activating fusions such as ETV6-NTRK3 or BTBD1-NTRK3 have oncogenic potential in some subsets of high-grade glioma." (PMID 35852875, 2022).
medullary thyroid carcinoma (3 papers, 2016 to 2020). "This is the first study showing the results of ETV6/NTRK3 rearrangement in medullary thyroid cancer." (PMID 28181547, 2017).
Obesity (3 papers, 2019 to 2022). Accumulation of substantial excess body fat. "Additionally, we observed that miR-122 inhibition had a stronger effect in the sWAT, resulting in upregulation of direct target genes with beneficial effects on obesity—including Vav1, whose knockout displayed increased fat content by decreasing Sirt1 activity; or Ntrk3, which promotes browning." (PMID 36499248, 2022).
soft tissue sarcoma (3 papers, 2022 to 2024). A malignant neoplasm arising from muscle tissue, adipose tissue, blood vessels, fibrous tissue, or other supportive tissues excluding the bones. "We present a novel clinical experience discussing the surgical treatment and reconstruction of a neurotrophic receptor tyrosine kinase type 3 (NTRK3) soft tissue sarcoma (STS) arising from the occipitalis muscle." (PMID 39717285, 2024). "We present a multidisciplinary approach to the treatment of a neurotrophic receptor tyrosine kinase type 3 (NTRK3) soft tissue sarcoma (STS), arising from the occipitalis muscle." (PMID 39717285, 2024).
chronic lymphocytic thyroiditis (2 papers, 2021 to 2024). "PTC patients with a history of Hashimoto’s disease showed a positive correlation of having NTRK3 and/or ETV6 fusion mutations as well." (PMID 39409115, 2024). "Both NTRK3 and ETV6 fusion mutations showed a marked positive correlation with Hashimoto’s thyroiditis with an approximate 13-fold and 21-fold increased likelihood of their co-occurrence with the disease compared to other cases in the cohort, respectively." (PMID 39409115, 2024). "Further, the more conventional statistical analysis identified significant associations of NTRK3 and ETV6 fusions with Hashimoto’s disease, plus in the case of ETV6, with endometriosis." (PMID 39409115, 2024). "NTRK3 and ETV6 fusions showed significant associations with Hashimoto’s disease, and ETV6, also with endometriosis." (PMID 39409115, 2024).
congenital heart disease (2 papers, 2016 to 2021). "A number of patients with congenital heart disease were shown to have mutations in the TrkC (NTRK3) gene." (PMID 34069424, 2021). "In addition, mutations of Ntrk3 gene have been shown in the development of human congenital heart diseases." (PMID 27496100, 2016).
liposarcoma (2 papers, 2023 to 2024). A usually painless malignant tumor that arises from adipose tissue. "Only two cases (1 NTRK1 and 1 NTRK3) with amplification were seen in well-differentiated liposarcoma samples." (PMID 39839837, 2024). "In a study trying to find NTRK fusion in solid tumors, one retroperitoneal liposarcoma showed double NTRK3 fusions (MORF4L1:NTRK3 and PPFIA2:NTRK3)." (PMID 39839837, 2024).
liver cancer (2 papers, 2016 to 2018). An epithelial or non-epithelial malignant neoplasm that arises from the liver. "In order to detect the expression of the target gene NTRK3 in clinical specimen, liver cancer tissues and paracarcinoma tissues were used to perform immunochemistry study." (PMID 27351280, 2016). "We found that NTRK3 were down-regulating in liver cancer patient specimens compared with paracancerous specimens." (PMID 27351280, 2016). "Our results showed that the expressions of NTRK3 were down-expressed in human liver cancer tissues compared with paracarcinoma tissues." (PMID 27351280, 2016).
mental disorder (2 papers, 2019 to 2020). A disease that has its basis in the disruption of mental process. "NTRK3 gene is compelling in the multiple mental disorders, and its rs16941321 SNP is only discriminating between these two ethnic groups from Cameroon." (PMID 31630246, 2020). "SNPs with the highest PIP from this region are mapping to gene NTRK3 that encodes a member of the NTRK family and has been reported to be associated with bipolar and other psychiatric disorders." (PMID 31745092, 2019).
multiple myeloma (2 papers, 2019 to 2021). "Still, the MATCH basket trial is looking to enroll patients with both solid and liquid malignancies, including multiple myeloma, harboring NTRK1, NTRK2, or NTRK3 gene fusions into the larotrectinib subprotocol (NCT02465060)." (PMID 35127532, 2021).
oligodendroglioma (2 papers, 2024). A well-differentiated (WHO grade II), diffusely infiltrating neuroglial tumor, typically located in the cerebral hemispheres. "Taken together, these data support that the ETV6::NTRK3 fusion present in the oligodendroglioma (grade II) could be a driver to promote tumor growth in vivo, suggesting that NTRK inhibitors may be a valuable therapeutic option to delay or avoid the need for radiotherapy in this population." (PMID 39087020, 2024).
osteosarcoma (2 papers, 2020 to 2024). A usually aggressive malignant bone-forming mesenchymal neoplasm, predominantly affecting adolescents and young adults. "The second analysis of a locally recurring osteosarcoma of a 22‐year old female revealed an intra‐chromosomal rearrangement between NTRK3 and the VPS18 gene that was likely generated through chromothripsis of chromosome 15." (PMID 32022484, 2020).
stomach adenocarcinoma (2 papers, 2021 to 2024). "Among these genes, MAP2K4 and NRAS are reported as driver genes by IntOGen, while NTRK3 is listed as a driver gene for esophageal cancer and stomach adenocarcinoma." (PMID 39554798, 2024).
thymoma (2 papers, 2021 to 2023). A neoplasm arising from the epithelial cells of the thymus. "For patients with types A and B1/B2 thymoma (n = 9), seven gene mutations, including MTOR, BRCA1, APC, NF1, HRAS, NTRK3, and PTCH1, were detected, and each gene appeared only once in patients with non-TCs+type B3 TETs." (PMID 34307137, 2021).
Tinnitus (2 papers, 2024 to 2025). Tinnitus is an auditory perception that can be described as the experience of sound, in the ear or in the head, in the absence of external acoustic stimulation. "In tinnitus, the predominant activity is that of other proteins, namely, the top key proteins BDNF/NTRK3/NTRK1/NTF3 in interaction with a number of Top2 key proteins, all members of the IEGs." (PMID 39062188, 2024). "The in-depth analysis of the targets of NTRK3/NTRK1/NTF3 under physiological and tinnitus conditions could help to create new starting points for therapeutic considerations." (PMID 39062188, 2024). "The key proteins NTRK3, NTRK1, and NTF3 in tinnitus are not simply involved in activating or inhibiting processes but in remodeling of synaptic transmission processes." (PMID 39062188, 2024).